S100A4 (S100 calcium binding protein A4)
Diseases named in the same sentence as S100A4 in open-access papers (continued):
Sharing a sentence is not in itself a finding about the gene and the disease.
cancer (continued). "However, the markers of invasion S100A4 and TNNT1 were found to be similar in both types of cancer at this stage of disease." (PMID 40433700, 2025). "There is a crosstalk between cancer cells and CAFs via CLDN18.2 and S100A4 accordingly." (PMID 40647419, 2025). "The purported interaction between S100A4 and CD5 may have implications in other disease contexts, such as cancer, given the ability of CD5 to downregulate T cell response." (PMID 40078995, 2025). "In a previous study, S100A4 protein was overexpressed in cultured cancer cells; the results showed that S100A4 protein overexpression did not significantly affect the proliferation of MCF-7 cells but inhibited the proliferation of MDA-MB-231 cells." (PMID 38872805, 2024). "From 25 human S100 proteins, we focused our attentionon S100A4 because of its well-established role in cancer progressionand metastasizes by interacting with nonmuscle myosin II (NMII)." (PMID 39425667, 2024). "In addition, S100A4 knockdown decreased the expression of MMP2, a promoter and mediator of EMT in cancer." (PMID 37033662, 2023). "Although for most S100s, and for HMGB1, the transcript levels were lower in the control HPNE cells than in the cancer cell lines, this was not the case for S100A4, S100A6, S100A7, S100A12, and S100A13." (PMID 37627239, 2023). "β-catenin binds transducin beta-like protein 1 (TBL1/TBLR1), and this complex stimulates the expression of several Wnt/APC/β-catenin pathway target genes, including proliferative factors, such as S100A4 or collagen triple helix repeat containing-1 (CTHRC1), identified as cancer-related proteins." (PMID 35913675, 2023). "S100A4 takes part in the EMT, with considerably high expression in the invasive facade of cancers." (PMID 37970208, 2023). "Our results clearly indicate that cantharidin and, to a lesser extent, its analogue norcantharidin are promising compounds for efficient anti-metastatic therapy targeting the metastasis-inducing genes S100A4 and MACC1 for personalized medicine for cancer patients." (PMID 36674695, 2023). "Both S100A4, a calcium-binding protein, and IGFBP2, an insulin-like growth factor-binding protein have roles in a multitude of cancer hallmarks including proliferation, angiogenesis, migration, invasion, and epithelial‐to‐mesenchymal transition, but their roles in CLL have not been characterized." (PMID 35301276, 2022). "We propose that ZIP1+S100A4+CX43high CAF may be called zinc-transport CAF (zCAF), which absorbs and transfers Zn2+ to neighbouring cancer cells through gap junctions." (PMID 36207295, 2022). "S100a4 is not an essential gene, since S100a4−/− mice are viable and fertile, supporting its favorable safety profile as a potential anti-cancer therapeutic." (PMID 35140215, 2022). "The angiogenic action of S100A4 occurs in a cell-specific manner not affecting the motility of cancer cells and fibroblasts." (PMID 34209679, 2021). "The data showed that S100A4, S100A14 and S100A16 were significantly higher in PDAC tissues compared with their counterparts, but the protein level of S100A2, S100A6 and S100A10 were similar between cancer tissues and their counterparts." (PMID 34530774, 2021). "S100A4 (spot 4001) was strongly downregulated in the 2D-PAGE proteomic analysis and this was confirmed by the western blot analysis which also showed strong downregulation of the protein in the SW480 cancer cell line." (PMID 32422974, 2020). "We also studied the S100A4 as an inhibitor—it blocking the interface of the V domain and S100A1 to stop the cell proliferation and could be used as the treatment of cancer and RAGE related disease." (PMID 30779808, 2019). "Although S100A4 is classified as a gene related to angiogenesis, but not EMT, in the cancer hallmark collection of Molecular Signatures Database (MSigDB), it is annotated in gene ontology EMT biological process, which can be supported by previous studies." (PMID 31581665, 2019).
cancer (continued). "Furthermore, targeting S100A4 significantly reduced the invasive capabilities of OSCC cells, suggesting that it is not only a marker of cancer invasiveness, but also a key determinant of the metastatic phenotype of OSCC." (PMID 30970087, 2019). "In addition to our study of the role of S100A4 in regulating MDSC apoptosis, multiple reports have focused on its role in cancer progression, specifically its ability to enhance metastasis." (PMID 29556233, 2018). "S100A4, a marker of EMT phenotype and also a critical regulator of cancer growth and metastasis, was recognized as a potential target molecule of miR-296, because the complementary sequence of miR-296 was identified in the 3’-UTR of S100A4 mRNA by TargetScan analysis." (PMID 28209128, 2017). "Elevated S100A4 level is shown to be involved in cancer cell motility and aggressiveness by the activation of non-muscle myosin." (PMID 29069865, 2017). "A previous study has designed and developed a conformationally constrained helical peptide model of non-muscle myosin peptide to bind to S100A4 with a dissociation constant in the nanomolar range, for specifically inhibiting motility of cancer cells." (PMID 29069865, 2017). "Given that S100A4 is an established metastasis-promoting protein, it is not surprising that this S100A4/MMP9 pathway is demonstrated in other cancer types." (PMID 27127879, 2016). "Currently, there is no clinically available treatment targeting S100A4 and its pleiotropic roles in cancer progression." (PMID 27127879, 2016). "Undifferentiated carcinomas cells show strong S100A4 expression, whereas bile ducts and hepatocytes lacked S100A4 expression." (PMID 27323406, 2016). "We confirmed these findings by western blot analysis, which showed a 3-fold increase of IL-8 expression in MDA-MB-231 cancer cells grown in 10% FBS and almost a 6-fold increase in S100A4 protein expression when cells are grown in the reduced concentration (0.1%) of FBS." (PMID 25776572, 2015). "Elevated expression of S100A4 has been found in numerous cancer types; its expression in non-metastatic cell lines was shown to trigger a more metastatic phenotype, whereas decreased S100A4 expression was associated with a lower metastatic capacity." (PMID 25310523, 2014). "Taken together, our results suggest that S100A4 contributes to cancer cell migration but not the resistance to anticancer drugs." (PMID 25310523, 2014). "Furthermore, S100A4 mRNA and protein levels were found to be upregulated in methotrexate (MTX)-resistant cancer cells and to contribute to MTX resistance." (PMID 25310523, 2014). "S100A4, a member of the S100 family of Ca2+-binding proteins, modulates the motility of both non-transformed and cancer cells by regulating the localization and stability of cellular protrusions." (PMID 24252706, 2013). "Given this close link between the S100A4 protein and TG2 and their ability to affect cell cancer cell migration our objective in this paper was to explore the potential involvement of TG2 in regulating S100A4-related cell migration and to elucidate the mechanisms involved." (PMID 23469180, 2013). "We found that SFPQ/S100A4 formed a complex in those cancer cells but not in normal bronchial cells." (PMID 40770831, 2025). "A growing list of biomarkers, e.g., α-smooth muscle actin (α-SMA), S100A4/fibroblast specific protein 1 (FSP-1), fibroblast activation protein (FAP), etc., have been used to define activated CAFs and CAFs are a potential therapeutic target for cancer treatment." (PMID 38410801, 2024). "Although previous studies concluded that S100A4 could interact with the following membrane receptors, including RAGE, EGFR, ERBB2, TLR4, and IL10R, these findings were derived from the nervous system or cancer-related studies." (PMID 36361563, 2022).
cancer (continued). "Here we report on a novel MACC1-β-catenin-S100A4 axis and demonstrate that, based on this rationale, combined transcriptional inhibition of MACC1 and S100A4 restricts cancer cell motility and metastasis in CRC with seminal cross entity potential for cancer therapy." (PMID 36008464, 2022). "Further supporting the importance of S100 specific members in cell motility and cancer metastasis, matrix metalloproteinase (MMP) expression/activity and degradation of the extra-cellular matrix (ECM) is also under the control of S100 proteins such as S100A4, S100A8, S100A9, S100A10 and S100A14." (PMID 36232334, 2022). "Interestingly, despite the lack of evidence for the involvement of S100A4 in iPSC generation, expression of this gene has been reported in adult stem cells and cancer stem cells." (PMID 33805347, 2021). "In addition, the nuclear expression of S100A4, as a nuclear transcription factor, regulates the expression of matrix metalloproteinase- (MMP-) 13 and degrades the extracellular matrix to promote cancer invasion." (PMID 33273928, 2020). "CMap drugs of 10 μM are usually used to treat cancer cells and generate gene expression signatures, therefore the inability of other S100A4-inhibitory drugs to reverse HMGA2-driven gene signature might be due to the higher doses required for S100A4 inhibition." (PMID 31581665, 2019). "S100A4 is a target gene of the Wnt/β-catenin signaling pathway, which is constitutively active in the majority of CRC and the intervention by targeting S100A4 may be a promising approach to inhibit cancer metastasis." (PMID 29069865, 2017). "Carcinomas in S100A4 knockout mice do not metastasise to the brain." (PMID 27100728, 2016). "At least in the mouse model, the peptide-based drugs against S100A4 have a potential as a novel antiangiogenic therapeutic agent, which is involved in starvation tactics-type anticancer drugs pioneered by Folkman, for both S100A4-positive cancers and -negative cancers." (PMID 26029719, 2015). "However, in liver which contained metastases, there was strong staining of the carcinoma cells for S100A4 mRNA with the antisense probe, but not with the sense probe, under the same conditions." (PMID 11875708, 2002). "The upregulation of tyrosine tRNA in the absence of S100A4 may therefore reflect an adaptive response to this altered signaling, highlighting a potential link between S100A4 mediated signaling and metabolic shifts in cancer cells." (PMID 40386382, 2025). "Although MACC1 and S100A4 are involved in different biological pathways, that is, MACC1 as a key regulator of HGF‐MET signaling and S100A4 as a transcriptional target of β‐catenin/T‐cell factor signaling, our data suggest that MACC1 and S100A4 might be co‐regulated in cancer." (PMID 30927479, 2019). "Both noninvasive and invasive cancer cells can express the EMT markers β-catenin and vimentin or S100A4, so these are also not unique to CAFs." (PMID 36010899, 2022). "Based on the Oncomine database, there are no obvious distinctions in S100A1, S100A4, S100A5, S100A6, and S100A13 expressions between cancer tissues and normal colon mucosa, and S100A7, S100A12, and S100Z are slightly overexpressed in CRC tissues." (PMID 33294444, 2020). "In conclusion, the present study confirms that nuclear S100A4 is a negative prognostic biomarker in patients with stage II and III carcinoma of the colon or rectum." (PMID 27273130, 2016). "S100A4 protein was expressed in the cytoplasm of node negative IDC and ILC, whereas decreased in more advanced cancer (node positive)." (PMID 18771601, 2008).
cancer (continued). "For instance, S100A4 can interact with multiple intracellular proteins (non-muscle myosin heavy chain (NMMHC) IIA, tropomyosin, and actin) that can result in changes in cell migration, explaining the role of S100A4 as promoting cancer metastasis." (PMID 37627239, 2023).
infection (11 papers, 2017 to 2025). The state of being infected such as from the introduction of a foreign agent such as serum, vaccine, antigenic substance or organism. "Multiplex IF staining revealed a significant increase in both the number of F4/80+CD11b+S100a4+ cells and in collagen I levels within the testes and epididymis after infection." (PMID 41031892, 2025). "Two different CD4 T-cell clusters expressing high levels of CCR6+ and S100A4+ appeared late post-infection in young and aged animals, respectively." (PMID 38771046, 2024). "When they were challenged with ZIKV, ZIKV antigen was observed in most of them, and viral RNA was detected and increased with time, indicating a replicable infection occurred in S100A4+ macrophages." (PMID 33315931, 2020). "S100A4 is likely expressed by some resident cells such as microglial in the brain, other than myeloid macrophages recruited during infection." (PMID 33315931, 2020). "In the present study, we found that S100A4 contributes to bacterial colonization at sites of infection." (PMID 28935867, 2017). "We characterized the localization of C. rodentium in colon tissue by fluorescence in situ hybridization (FISH) on day 0 and day 7 in WT and S100A4−/− mice after infection." (PMID 28935867, 2017). "Levels of some chemokines and cytokines, such as MIP-2, MCP-1, IL-6, IL-17A, and IFN-γin colons were significantly attenuated in S100A4−/− mice after C. rodentium infection, which suggested reduced inflammation during early infection." (PMID 28935867, 2017). "However, S100a4 was also expressed by F4/80hi macrophages at day 14 after infection, suggesting local differentiation of S100a4+ monocytes into tissue macrophages in both the testis and epididymis." (PMID 41031892, 2025). "Therefore, our forthcoming research will concentrate on investigating pyroptosis induced by Mtb H37RV and H37RA infections in macrophages and S100A4−/− mice." (PMID 37628889, 2023). "The results showed a significantly suppression of epithelial marker genes E-cadherin, collagen IV and cytokeratin, as well as increased expression of mesenchymal marker genes N-cadherin, snail, vimentin and S100A4 at 12 h after infection with SH0165 (108 CFU/mL)." (PMID 30258822, 2018). "The differences between infection in S100A10 KO versus A2t KO cells could be explained by the fact that S100 family members S100A4, S100A6, and S100A11 are also able to complex with AnxA2 and are expressed in cervical epithelium." (PMID 30076379, 2018). "Furthermore, CT26 cells were treated with S100A4 for 0–8 h before infection with C. rodentium for 1 h." (PMID 28935867, 2017). "Furthermore, C. rodentium colonization of colons in S100A4−/− mice was significantly less than those in WT mice after infection on day 7 (P < 0.05)." (PMID 28935867, 2017). "Infection-induced inflammation and colonic pathology are attenuated in S100A4−/− mice." (PMID 28935867, 2017). "Consequently, infection by heterogeneous PRRSV strains was markedly inhibited in S100A4-transfected MARC-145 cells compared to inhibition observed for EV-transfected cells measured by Anti-N Mab-6D10 except for PRRSV-1 strains due to the antigenic variation of N protein." (PMID 31649651, 2019). "Therefore, we determined the role of S100A4 during infection of primary macrophages." (PMID 28935867, 2017). "First, we validated the efficient infection of AAV9-S100A4 KD and the expression of S100A4 in mouse arterial tissues." (PMID 38164183, 2024). "S100A4+ macrophages had higher viability than spermatogenic cells, which allowed them to be the main target cells for ZIKV replication when spermatogenic cells were destroyed at the late stage of infection." (PMID 33315931, 2020). "Electron microscopic observation thus provided further evidence that S100A4+ macrophages were more robust and could support ZIKV replication at the late stage of infection when spermatogenic cells diminished." (PMID 33315931, 2020).
infection (continued). "Therefore, S100A4 may effectively inhibit MYH9 aggregation, as supported by its efficacy in inhibiting infection of permissive cells by all PRRSV isolates tested." (PMID 31649651, 2019). "Moreover, overexpression of S100A4, a MYH9-specific disassembly inducer, in MARC-145 cells significantly resulted in diminished MYH9 aggregation and marked inhibition of subsequent virion internalization and infection by both PRRSV-1 and PRRSV-2 isolates." (PMID 31649651, 2019). "However, S100A4 does not seem to play a protective role during infection." (PMID 28935867, 2017). "However, we did not found significantly decrease of cDC infiltration in S100A4−/− mice, suggesting that S100A4 maybe not obviously affect the recruitment of cDC after infection, and whether the function of cDC could be affected by S100A4 still need further study." (PMID 28935867, 2017). "Interestingly, introduction of S100A4 protein expression within MARC-145 cells significantly diminished MYH9 aggregation and ultimately inhibited PRRSV internalization and sequential infection regardless of PRRSV genotype." (PMID 31649651, 2019).
adenocarcinoma (10 papers, 2002 to 2022). A common cancer characterized by the presence of malignant glandular cells. "In principal, the same associations were found between nuclear S100A4 expression and the mentioned clinicopathological parameters both in the whole patient cohort, and when analyzing the adenocarcinoma group separately." (PMID 22853000, 2012). "In our previously published report we found that S100A4 expression was associated with smaller, highly differentiated NSCLC tumors and that S100A4 had a significantly higher expression in adenocarcinomas compared to the other histological subtypes." (PMID 24215488, 2013). "Expression levels of S100A4 and ephrin-A1 were significantly higher in adenocarcinomas compared to other histological subtypes, and S100A4-positive tumors were smaller and more differentiated than tumors without expression." (PMID 22853000, 2012). "Interestingly, we found that adenocarcinomas had a higher percentage of S100A4 and ephrin-A1 positivity compared to squamous and large cell tumors, and this finding is in keeping with that of previous studies on S100A4 and ephrin-A1." (PMID 22853000, 2012). "S100A4 was a negative prognostic factor in several subgroups of adenocarcinoma patients, but not in the overall patient cohort." (PMID 24215488, 2013). "To characterize these factors, we performed a differential screening with CM from metastatic mouse adenocarcinoma cell line VMR revealing stimulatory effect on S100A4 release from fibroblasts and inactive CM from nonmetastatic mouse adenocarcinoma CSML0." (PMID 20442771, 2010). "In addition, in the adenocarcinomas, S100A4 had negative prognostic impact also in stage I and in lymph node negative patients." (PMID 24215488, 2013).
kidney disease (5 papers, 2007 to 2022). "S100A4 was also shown to be a prognostic marker for kidney disease." (PMID 29556233, 2018). "It was proven that in fibrotic kidney disease tubulus epithelial cells can transdifferentiate to fibroblasts expressing the fibroblast-specific protein 1 (FSP-1), also known as S100A4 calcium-binding protein, and are able to express collagens." (PMID 17663771, 2007).
inflammation (4 papers, 2021 to 2023). Aberrant reaction of the microcirculation characterized by movement of fluid and leukocytes from the blood into extravascular tissues. "We hypothesized that the potential role of S100A4 in asthmatic airway inflammation may be partially attributed to its ability to promote the infiltration of inflammatory cells." (PMID 37873538, 2023).